PNPO (pyridoxamine 5'-phosphate oxidase)
Description:
Catalyzes the oxidation of either pyridoxine 5'-phosphate (PNP) or pyridoxamine 5'-phosphate (PMP) into pyridoxal 5'-phosphate (PLP).
Synonyms: PDXPO; HEL-S-302
Tractability: Small molecule: a structure with a bound ligand is known. PROTAC: ubiquitination databases record sites on it; its protein half-life has been measured; a small molecule that binds it is known.
Target class: Enzyme; Oxidoreductase
Gene: Protein-coding gene on chromosome 17 (47,941,506 to 47,949,308, forward strand). Ensembl gene ENSG00000108439.
Subcellular location (Human Protein Atlas): Cytosol; Nucleoplasm
Pathways (Reactome):
Metabolism: Vitamin B6 activation to pyridoxal phosphate
Gene Ontology:
Molecular function: FMN binding; protein binding; protein homodimerization activity; pyridoxal phosphate binding; pyridoxamine phosphate oxidase activity; oxidoreductase activity, acting on the CH-NH2 group of donors
Biological process: pyridoxal phosphate biosynthetic process; pyridoxine biosynthetic process; vitamin B6 metabolic process
Cellular component: mitochondrion; cytosol
Genetic constraint (gnomAD): Loss-of-function variants: 32 observed, 29.02 expected, observed/expected ratio (o/e) 1.1, 90% interval 0.83 to 1.48. The upper end of that interval is the gene's LOEUF score, 1.48, which puts it in group 6 of 6, group 1 being the genes least tolerant of losing a copy. Missense variants: 288 observed, 328.44 expected, observed/expected ratio (o/e) 0.88, 90% interval 0.8 to 0.97. Synonymous variants: 115 observed, 115.68 expected, observed/expected ratio (o/e) 0.99, 90% interval 0.85 to 1.16.
Gene-disease validity (ClinGen):
ClinGen rates the evidence that PNPO causes each of these diseases.
pyridoxal phosphate-responsive seizures (autosomal recessive): Definitive. A very rare neonatal epileptic encephalopathy disorder characterized clinically by onset of severe seizures within hours of birth that are not responsive to anticonvulsants, but are responsive to treatment with pyridoxal phosphate.
Homologues: Orthologues: chimpanzee PNPO (100% identical), macaque PNPO (98% identical), dog PNPO (92% identical), rabbit PNPO (91% identical), mouse Pnpo (90% identical), pig PNPO (90% identical), rat Pnpo (90% identical), guinea pig PNPO (85% identical), zebrafish pnpo (56% identical), Drosophila melanogaster sgll (41% identical), Caenorhabditis elegans F57B9.1 (39% identical).
Diseases named in the same sentence as PNPO in open-access papers:
PNPO is named in the same sentence as 89 diseases in open-access papers, as found by Europe PMC text mining. Sharing a sentence is not in itself a finding about the gene and the disease. The quoted sentences say what the papers report.
epilepsy (16 papers, 2015 to 2025). A brain disorder characterized by episodes of abnormally increased neuronal discharge resulting in transient episodes of sensory or motor neurological dysfunction, or psychic dysfunction. "The increasingly recognized impact of PNPO in epilepsy raises the question of how PNPO variants are implicated in different types of epilepsy and ages of seizure onset." (PMID 35217610, 2022). "This genetically tractable model system and well-controlled dietary conditions have enabled the functional and molecular characterization of three epilepsy-associated PNPO alleles with vastly different phenotypes." (PMID 35217610, 2022). "We generated knock-in flies carrying different epilepsy-associated pyridox(am)ine 5′-phosphate oxidase (PNPO) alleles and studied the developmental, behavioral, electrophysiological, and fitness effects of each mutant allele under different dietary conditions." (PMID 35217610, 2022). "In summary, our studies uncover a diversity of molecular defects of PNPO variants, reveal the role of the PNPO allele–diet interaction in the phenotype expression, and highlight the contribution of PNPO deficiency to epilepsy in general." (PMID 35217610, 2022). "PLPBP deficiency, however, is another B6‐dependent epilepsy associated with low‐CSF‐PLP akin to PNPO deficiency." (PMID 32888189, 2021). "It is important to differentiate between PNPO deficiency and other B6‐dependent epilepsies, including alpha‐aminoadipic semialdehyde dehydrogenase (ALDH7A1) deficiency and pyridoxal phosphate‐binding protein (PLPBP) deficiency." (PMID 32888189, 2021). "The patient with a suspicion of PNPO deficiency presented neonatal epilepsy associated with a profound CSF PLP deficiency, increased CSF amino acids and normal biogenic amines." (PMID 27243974, 2016). "PNPO deficiency has been linked to neurodevelopmental impairment and epilepsy." (PMID 37845746, 2023). "Recently, the PNPO gene has also been implicated in epilepsy in adults." (PMID 35217610, 2022). "Therefore, human carriers of such a category of PNPO mutations could be susceptible to epilepsy and related disorders." (PMID 35217610, 2022). "Therefore, it will be important to examine whether mild PNPO deficiency caused by R116Q can be exacerbated by other genetic and/or environmental factors to cause epilepsy or other diseases in humans." (PMID 35217610, 2022). "PLP-dependent epilepsy is rarer than PDE and is related to Pyridox(am)ine phosphate oxidase (PNPO) deficiency, i.e., the enzyme that catalyzes the reaction from Pyridoxine-phosphate or Pyridoxamine-phosphate to PLP." (PMID 33748042, 2021). "PNPO has been known to play a part in human epilepsy, and some research displayed that PNPO has played a role in the development of ovarian, breast, and colorectal cancers." (PMID 35127701, 2021). "Given the amenability of PNPO‐dependent epilepsy to treatment with PLP and PN therapy for optimal seizure control and favorable developmental outcomes, early diagnosis is essential." (PMID 32888189, 2021). "PNPO, which served as a key enzyme in the metabolism of vitamin B6, has primarily been studied in the context during the development of epilepsy." (PMID 35127701, 2021). "In humans, mutant PNPO results in a specific form of epilepsy known as pyridoxal-phosphate dependent epilepsy (PPDE)." (PMID 34001919, 2021). "Vitamin B6-responsive epilepsies are a group of genetic disorders including ALDH7A1 deficiency, PNPO deficiency, and others, usually causing neonatal onset seizures resistant to treatment with common antiepileptic drugs." (PMID 31741821, 2019). "The clinical targeted next generation epilepsy panels include PDE-ALDH7A1, PNPO and GLUT1 deficiencies and dystonia panels include TH, GTPCH, GLUT1, SR and dopamine transporter deficiencies." (PMID 25758715, 2015). "Hence, diagnosis of different B6‐dependent epilepsies is best established by the identification of biallelic pathogenic variants in the ALDH7A1, PNPO and PLPBP genes." (PMID 32888189, 2021).
ovarian carcinoma (9 papers, 2013 to 2025). A malignant neoplasm originating from the surface ovarian epithelium. "In addition, TGF-β is able to upregulate the expression of PNPO (pyridoxamine 5′-phosphate oxidase), which encodes the rate-limiting enzyme in vitamin B6 metabolism, to produce active forms of vitamin B6 that may promote ovarian cancer progression." (PMID 35359452, 2022). "The previous studies showed that PNPO was upregulated in ovarian cancer and human breast invasive ductal carcinoma patients." (PMID 35127701, 2021). "We found that TGF-β1 signaling-mediated PNPO expression was at least partially mediated by the upregulation of miR-143–3p in ovarian cancer." (PMID 35127701, 2021). "Our previous studies confirmed that PNPO was overexpressed in ovarian cancer and enhanced the malignant biology function of ovarian cancer cells, indicating that PNPO is a candidate oncogene role in tumorigenesis." (PMID 35127701, 2021). "Despite the lack of negative control tissue of the ovary in this array, we found that PNPO staining was strong in ovarian cancer tissues (n = 6)." (PMID 35127701, 2021). "Our previous study has shown that pyridoxine 5′-phosphate oxidase (PNP oxidase, PNPO) is overexpressed in human ovarian cancer and is a potential tumor progression marker." (PMID 30982780, 2019). "For instance, a gene array study reported that PNPO is upregulated in colorectal cancer and can predict overall survival and is one of the important molecules involved in ovarian cancer development." (PMID 30982780, 2019). "Our previous study showed that pyridoxine 5'-phosphate oxidase (PNPO) is a tissue biomarker of ovarian cancer (OC) and has a prognostic implication but detailed mechanisms remain unclear." (PMID 38615082, 2024). "In our previous study, it was unveiled that increased PLP could inhibit the protein expression of PNPO, thus suppressing the proliferation of human ovarian cancer cells." (PMID 35127701, 2021). "Then we examined the correlation of PNPO with seven hub genes via TCGA ovarian cancer datasets." (PMID 34322485, 2021). "However, the role of PNPO and its regulatory mechanism in epithelial ovarian cancer (EOC) are unknown." (PMID 29238081, 2017). "PNPO activity affects PLP product and the biological behavior of ovarian cancer cells and has an influence on colorectal cancer." (PMID 30982780, 2019). "Pyridoxine 5′-phosphate oxidase (PNPO), a converting enzyme for the active form of vitamin B6, pyridoxal 5′-phosphate (PLP), is overexpressed in human ovarian cancer, and PNPO suppression can inhibit proliferation, migration, invasion and colony formation of breast cancer cells." (PMID 38475720, 2024).
breast carcinoma (6 papers, 2017 to 2025). "Knockdown of PNPO affected breast cancer cell behavior and was associated with PR expression." (PMID 30982780, 2019). "PNPO was reported as an oncogene to promote cell proliferation, migration, and invasion, and regulate cell cycle and apoptosis in ovarian and breast cancer cell lines." (PMID 35127701, 2021). "Suppression of PNPO can inhibit breast cancer cell proliferation, migration, invasion and colony formation, and promote cell apoptosis." (PMID 30982780, 2019). "PNPO was down-regulated and up-regulated by miR-216b-5p mimics and inhibitors, respectively, in breast cancer cells." (PMID 30982780, 2019). "Suppression of PNPO inhibited breast cancer cell proliferation, migration, invasion and colony formation, arrested cell cycle at the G2/M phase and induced cell apoptosis." (PMID 30982780, 2019). "We found that knockdown of PNPO resulted in a decrease of breast cancer cell proliferation, migration, invasion, and colony formation, arrested cell cycle at the G2/M phase, and induced cell apoptosis." (PMID 30982780, 2019). "Besides, PNPO positively correlated with MALAT1 in breast cancer cells, whereas MALAT1 was negatively correlated with miR-216b-5p, suggesting a ceRNAs regulatory mechanism." (PMID 38475720, 2024). "Furthermore, the correlation of PNPO expression with the breast cancer hormone therapy-related markers such as estrogen receptor (ER), progesterone receptor (PR) and human epidermal growth factor receptor-2 (HER2) is not clear." (PMID 30982780, 2019). "MALAT1/miR-216b-5p/PNPO may act as competing endogenous RNAs (ceRNAs) that affect the biological behavior of breast cancer cells and cancer progression." (PMID 30982780, 2019). "Because of the vast heterogeneity in breast cancer and because the regulation of PR due to PNPO knockdown in MCF-7 cells remains unknown, along with this line, further study may be needed." (PMID 30982780, 2019). "A regulatory mechanism of the MALAT1/miR-216b-5p/PNPO axis may be important in breast cancer development." (PMID 30982780, 2019). "Furthermore, the ceRNA mechanism in the regulation of PNPO was found in breast cancer cells." (PMID 30982780, 2019). "Furthermore, the concentration of serum PNPO was increased in breast cancer patients, suggesting that PNPO may serve as a serum marker for IDC detection." (PMID 30982780, 2019). "In this study, the expression and function of PNPO were examined in patients with IDC and breast cancer cells." (PMID 30982780, 2019). "The present study demonstrated for the first time that PNPO was upregulated in IDC at mRNA and protein levels and correlated with the overall survival of patients with breast cancer." (PMID 30982780, 2019). "In summary, we demonstrate for the first time that PNPO and MALAT1 are up-regulated, while miR-216b-5p is down-regulated, in human breast cancer." (PMID 30982780, 2019). "Using a CCK8 assay, a decrease of cell viability was observed in breast cancer cells MCF-7 and MDA-MB-231 after PNPO-shRNA infection." (PMID 30982780, 2019). "Most interestingly, we found that knockdown of PNPO increased the expression of PR-B isoform in MCF-7 cells, not in MDA-MB-231 cells, suggesting that PNPO may influence the hormone sensitivity of breast cancer cells." (PMID 30982780, 2019). "The expression of PNPO at the high and low levels was correlated with ER expression, but not PR, HER2, and a proliferation marker Ki-67, in breast cancer tissues (p = 0.04)." (PMID 30982780, 2019). "Nine years later in 2006, another report showed that PNPO is induced by estradiol and 4-hydroxytamoxifen in T47D and MCF7 breast cancer cells, but not in ERα-negative MDA-MB-231 breast cancer cells." (PMID 29238081, 2017).
colorectal cancer (5 papers, 2017 to 2021). A primary or metastatic malignant neoplasm that affects the colon or rectum. "Based on the Oncomine database, PNPO expression was higher expressed in colorectal cancer, leukemia, lymphoma, and myeloma compared to the human normal control tissues, while it was lower expressed in kidney cancer." (PMID 35127701, 2021). "PNPO combined with other six genes has been proven to be an independent prognostic index panel for OS in patients with colorectal cancer." (PMID 35127701, 2021). "For instance, a model of seven-gene signatures (NHLRC3, ZDHHC21, PRR14L, CCBL1, PTPRB, PNPO and PPIP5K2) was applied to predict OS by dividing colorectal cancer (CRC) patients into low-risk and high-risk groups." (PMID 28827775, 2017). "PNPO was also reported to be upregulated in colorectal cancer from a gene array study." (PMID 35127701, 2021).
Epileptic encephalopathy (4 papers, 2019 to 2026). A condition in which epileptiform abnormalities are believed to contribute to the progressive disturbance in cerebral function. "Pyridox(am)ine-5'-phosphate oxidase (PNPO) deficiency is characterized by early-onset epileptic encephalopathy refractory to standard antiseizure medications." (PMID 42016347, 2026). "PNPO deficiency, due to its gene mutations, has been widely studied in infantile and neonatal epileptic encephalopathy." (PMID 35127701, 2021). "Pyridoxamine-5′-phosphate oxidase (PNPO) deficiency is an autosomal recessive epileptic encephalopathy responsive to pyridoxal 5′-phosphate (PLP)." (PMID 35053812, 2021). "Altered vitamin B6 metabolism due to pathogenic variants in the gene PNPO causes early onset epileptic encephalopathy, which can be treated with high doses of vitamin B6." (PMID 31641590, 2019).
diabetes (3 papers, 2020 to 2025). "Studies aimed at correlating the expression of PDXK or PNPO human genes with diabetes are still scarce, but encouraging." (PMID 32456137, 2020).
genetic generalized epilepsy (3 papers, 2018 to 2022). A generalized epilepsy that is understood to have a genetic etiology. "We recently reported that single nucleotide polymorphisms (SNPs) that influence PNPO expression in the brain are associated with genetic generalized epilepsy (GGE)." (PMID 31641590, 2019).
Hypsarrhythmia (3 papers, 2022 to 2023). Hypsarrhythmia is abnormal interictal high amplitude waves and a background of irregular spikes. "Hypsarrhythmia was observed in 13 patients (7 with PNPO deficiency)." (PMID 36980111, 2023). "Significance: ES might be a common form of seizures in PNPO deficiency, and EEG presented as hypsarrhythmia or a burst suppression pattern." (PMID 35495162, 2022). "So, we considered that ES might be a common form of seizure with PNPO deficiency, and EEG presented as hypsarrhythmia or burst suppression pattern." (PMID 35495162, 2022). "Vitamin B6 allowed patients with ALDH7A1 and PNPO mutations to achieve seizure-free status, oxcarbazepine was effective for patients with SCN2A, ATP7A, WWOX, and PRRT2 mutations, and ACTH was partly effective for DOCK6 mutation patients with spasms and hypsarrhythmia." (PMID 35715422, 2022).
infantile spasms (3 papers, 2021 to 2022). A rare epilepsy syndrome characterized by onset of epileptic spasms in infants between 2 and 12 months of age, and rarely up to 24 months. "In our groups with PNPO deficiency diagnosed with infantile spasms, patient nine underwent a conversion from pyridoxine to PLP due to pyridoxine inefficacy." (PMID 35495162, 2022). "In their study, a patient with PNPO deficiency phenotypically diagnosed as infantile spasms responded well to PLP, with seizure control within 24 h but no response to pyridoxine." (PMID 35495162, 2022). "The review of the literature identified a single patient with PLP-dependent epilepsy due to PNPO deficiency who presented as a typical de novo West syndrome." (PMID 33748042, 2021). "In the etiologies of infantile spasms, especially genetic etiology, PDE, PNPO deficiency, and PLPBP deficiency account for only a rare proportion." (PMID 35495162, 2022). "In our PNPO deficiency cohort, patients with infantile spasms did not respond better to PLP than pyridoxine." (PMID 35495162, 2022). "The review of the literature found only one case of PNPO deficiency presenting as de novo West syndrome and no case of ATQ deficiency." (PMID 33748042, 2021). "Therefore, in our PNPO deficiency cohort, patients with infantile spasms did not respond better to PLP than pyridoxine." (PMID 35495162, 2022).
liver disease (3 papers, 2025 to 2026). "A 15‐year‐old boy with PNPO deficiency and cirrhosis underwent orthotopic liver transplantation for hepatocellular carcinoma without extra‐hepatic disease." (PMID 41527660, 2026).
PNPO deficiency (3 papers, 2021 to 2025). "Beyond classic ALDH7A1 mutations causing (PDE) and pyridox(am)ine-5’-phosphate oxidase (PNPO deficiency), the recent characterization of additional metabolic disorders—including hypophosphatasia and homocystinuria—has broadened the spectrum of vitamin B6-dependent epileptic syndromes." (PMID 41149778, 2025). "Several variants of the enzyme pyridox(am)ine 5′-phosphate oxidase (PNPO), responsible for a rare form of vitamin B6-dependent neonatal epileptic encephalopathy known as PNPO deficiency (PNPOD), have been reported." (PMID 34769443, 2021).
pyridoxine-dependent epilepsy (3 papers, 2015 to 2022). A rare neurometabolic disease characterized by recurrent intractable seizures in the prenatal, neonatal and postnatal period that are resistant to anti-epileptic drugs (AEDs) but that are responsive to pharmacological dosages of pyridoxine (vitamin B6). "Pyridoxine-dependent epilepsy (PDE, OMIM: 266100) or ALDH7A1 deficiency (traditionally) and pyridox(am)ine-5′-phosphate oxidase (PNPO) deficiency (OMIM: 610090) are the most prevalent type." (PMID 35495162, 2022).
Seizure (3 papers, 2022 to 2023). A seizure is an intermittent abnormality of nervous system physiology characterized by a transient occurrence of signs and/or symptoms due to abnormal excessive or synchronous neuronal activity in the brain. "Seizure onset mainly occurred in the neonatal period (67.8% of cases), while only ten patients presented with seizures after the age of 12 months (four with ALDH7A1 deficiency, three with PNPO deficiency, one with PLPBL, and two with hyperprolinemia type II)." (PMID 36980111, 2023).